MSH6 (mutS homolog 6)
Diseases named in the same sentence as MSH6 in open-access papers (continued):
Sharing a sentence is not in itself a finding about the gene and the disease.
Lynch syndrome (continued). "In this case, a loss of MSH6 with MSI-high status was observed in the tumor tissue, and germline mutation testing confirmed Lynch syndrome." (PMID 39186128, 2024). "For MLH1 and MSH6, our results support previous studies suggesting that sarcomas are rare manifestations of Lynch syndrome." (PMID 39594770, 2024). "Interestingly, all these genes are implicated in tumorigenesis.Indeed, MSH6 is a mismatch repair factor and its mutation is associated with Lynchsyndrome and cancer susceptibility 39.Overexpression of MSH6 might also exert an oncogenic function in glioblastoma by promotingcell proliferation." (PMID 39070636, 2024).
Lynch syndrome (continued). "Gene-related cancer predisposition syndromes accounted for 16.7% (4/24) of ACMG SFs: MSH6 Lynch syndrome—1, BRCA1 hereditary breast and ovarian cancer (HBOC)—1, and PALB2 hereditary breast cancer (HBC)—2." (PMID 36635046, 2023). "Here, we report the first case of a mosaic MSH6 gene pathogenic variant in an EC- and CRC-affected individual diagnosed with suspected Lynch syndrome." (PMID 37318702, 2023). "Lynch syndrome is a hereditary disease characterized by constitutive mutations in the DNA mismatch repair pathway (most commonly MLH1, MLH2, MSH6, or PMS2 genes)." (PMID 37370964, 2023). "In our study, TTN DCM type 1G, KCNQ1 LQTS type 1, MYBPC3 HCM type 4, and TMEM43 arrhythmogenic right ventricular dysplasia type 5 were the most frequent CVD, and MSH6 Lynch syndrome and PALB2 HBC were the most frequent CPC among ACMG SFs." (PMID 36635046, 2023).
Lynch syndrome (continued). "In this study, genetic analysis of the tumor in a 72-year-old male patient with refractory conventional chordoma of the skull base revealed a high tumor mutational burden (TMB) and mutations in the MSH6 and MLH1 genes, which are found in Lynch syndrome." (PMID 37086325, 2023).
Lynch syndrome (continued). "One patient who had developed two SMN (colon carcinoma and glioblastoma) and with suspicious family history was diagnosed with Lynch syndrome (MSH6)." (PMID 36097283, 2022).
Lynch syndrome (continued). "Universal tumour testing for Lynch syndrome revealed that MSH6 and PMS2 carriers are more frequent than previously recognized." (PMID 33916129, 2021). "Only 13% of path_MMR carriers in the clinically selected Prospective Lynch Syndrome Database bear path_MSH6." (PMID 33693762, 2021). "Even worse, the NGS laboratory report suggested the diagnosis of Lynch syndrome based on the presence of the MSH6 substitution with at best unproven clinical significance, which made an impact on further management of this patient." (PMID 33407806, 2021).